RN7SL18P (RNA, 7SL, cytoplasmic 18, pseudogene)
Gene: Miscellaneous RNA gene on chromosome 2 (62,491,178 to 62,491,468, forward strand). Ensembl gene ENSG00000241625.
Homologues: Orthologues: chimpanzee Metazoa_SRP (100% identical), macaque Metazoa_SRP (85% identical). Paralogues in human: RN7SL1 (88% identical), RN7SL2 (88% identical), RN7SL3 (87% identical), RN7SL448P (86% identical), RN7SL220P (84% identical), RN7SL147P (84% identical), RN7SL709P (84% identical), RN7SL664P (84% identical), RN7SL126P (83% identical), RN7SL464P (83% identical), RN7SL597P (83% identical), RN7SL652P (83% identical), and 705 more.